PTPRA (protein tyrosine phosphatase receptor type A)
Description:
Tyrosine protein phosphatase which is involved in integrin-mediated focal adhesion formation (By similarity). Following integrin engagement, specifically recruits BCAR3, BCAR1 and CRK to focal adhesions thereby promoting SRC-mediated phosphorylation of BRAC1 and the subsequent activation of PAK and small GTPase RAC1 and CDC42 (By similarity).
Synonyms: R-PTP-alpha; PTPA; PTPRL2; LRP; HLPR; HPTPA; RPTPA; HEPTP; HPTPalpha
Tractability: Small molecule: a high-quality ligand is known; it belongs to a druggable protein family. Antibody: its Gene Ontology location is reachable by antibodies, with high confidence; UniProt places it where antibodies can reach, with medium confidence; UniProt predicts a signal peptide or a membrane-spanning region. PROTAC: ubiquitination databases record sites on it; its protein half-life has been measured; a small molecule that binds it is known.
Target class: Enzyme; Protein Phosphatase; Receptor tyrosine-protein phosphatase; Tyrosine protein phosphatase; Phosphatase
Gene: Protein-coding gene on chromosome 20 (2,870,754 to 3,039,247, forward strand). Ensembl gene ENSG00000132670.
Subcellular location: Cell membrane; Cell junction, focal adhesion
Subcellular location (Human Protein Atlas): Vesicles; Nucleoplasm
Pathways (Reactome):
Developmental Biology: NCAM signaling for neurite out-growth
Signal Transduction: RAF/MAP kinase cascade
Gene Ontology:
Molecular function: protein binding; protein tyrosine phosphatase activity; transmembrane receptor protein tyrosine phosphatase activity
Biological process: integrin-mediated signaling pathway; regulation of focal adhesion assembly; signal transduction
Cellular component: extracellular exosome; receptor complex; focal adhesion; membrane; plasma membrane
Genetic constraint (gnomAD): Loss-of-function variants: 18 observed, 102.49 expected, observed/expected ratio (o/e) 0.18, 90% interval 0.12 to 0.26. The upper end of that interval is the gene's LOEUF score, 0.26, which puts it in group 1 of 6, group 1 being the genes least tolerant of losing a copy. Missense variants: 744 observed, 1,039.5 expected, observed/expected ratio (o/e) 0.72, 90% interval 0.67 to 0.76. Synonymous variants: 319 observed, 382.32 expected, observed/expected ratio (o/e) 0.83, 90% interval 0.76 to 0.92.
Homologues: Orthologues: chimpanzee PTPRA (99% identical), macaque PTPRA (99% identical), dog PTPRA (96% identical), rabbit PTPRA (96% identical), pig PTPRA (96% identical), mouse Ptpra (95% identical), rat Ptpra (94% identical), guinea pig PTPRA (94% identical), tropical clawed frog ptpra (82% identical), zebrafish ptpra (76% identical). Paralogues in human: PTPRE (58% identical), PTPRF (45% identical), PTPRS (45% identical), PTPRD (44% identical), PTPRK (32% identical), PTPRM (31% identical), PTPRT (31% identical), PTPRZ1 (31% identical), PTPRC (31% identical), PTPRG (30% identical), PTPRU (29% identical), PTPRB (19% identical), and 23 more.
Diseases named in the same sentence as PTPRA in open-access papers:
PTPRA is named in the same sentence as 31 diseases in open-access papers, as found by Europe PMC text mining. Sharing a sentence is not in itself a finding about the gene and the disease. The quoted sentences say what the papers report.
gastric cancer (5 papers, 2010 to 2020). A primary or metastatic malignant neoplasm involving the stomach. "The gastric cancer-related overexpression of PTPRA and MMP9 has previously been implicated but the association between copy number and overexpression has not been reported." (PMID 20187983, 2010). "The role of PTPRA in gastric cancer might be linked to its biological role in integrin signalling, cell adhesion, and activating the SRC family tyrosine kinases." (PMID 20187983, 2010). "Moreover, increased expression of the protein tyrosine phosphatase (PTPRA) gene and promoter methylation of the calcium-binding protein 39-like (CAB39L) gene were associated with gastric cancer." (PMID 31892232, 2019). "In addition to ERBB2 and PERLD1, the TRAC analysis also identified five novel genes, CYP3A4, ENAH, MMP9, PTPRA, and OSMR, which have not been reported as gained and overexpressed in gastric cancer before." (PMID 20187983, 2010).
schizophrenia (5 papers, 2014 to 2026). A major psychotic disorder characterized by abnormalities in the perception or expression of reality. "Recent whole exome sequence data, however, added new support, in the form of six new potentially damaging missense mutations, for a connection between PTPRA variants and schizophrenia." (PMID 36755664, 2022). "Mutations in PTPRA have been identified as segregating with disease in a family with schizophrenia and in other unrelated patients with this disease." (PMID 35900966, 2022). "We sequenced the protein-encoding areas of the PTPRA gene for single nucleotide polymorphisms or small insertions/deletions (InDel) in 382 schizophrenia patients." (PMID 25393624, 2014). "Indeed, for SNP rs1016753 they detected a link with schizophrenia, and reduced PTPRA mRNA levels were noted in postmortem brain specimens of schizophrenia subjects." (PMID 36755664, 2022). "Interestingly, rare variants in PTPRA were also recently found in a family study of schizophrenia, though their functional significance has not been elucidated." (PMID 35900966, 2022).
breast carcinoma (3 papers, 2012 to 2021). "Phosphorylated PTPRA at focal adhesions recruits a complex of breast cancer anti-estrogen resistance 3 (BCAR3) and p130Cas in addition to Grb2 and Src." (PMID 33710332, 2021). "PTPs can also promote invasion including PTPRU in glioma, PTPRJ in breast cancer, PTPRA in colon cancer and PTPRZ in gastric cancer." (PMID 33710332, 2021).
lung carcinoma (3 papers, 2022). "Elevated levels of PTPRA leads to promotion of lung cancer and is associated with poor prognosis and overall survival through c-Src activation." (PMID 36178190, 2022). "The present study aimed to examine the function of circRNA protein tyrosine phosphatase receptor type A (circRNA_PTPRA) in lung cancer cells and elucidate the underlying molecular mechanisms." (PMID 35549985, 2022). "In this study, we continue to focus on the germline mutation of genes in lung adenocarcinoma and we have identified seven different variants (SMG5, RAB3GAF2, EI24, XDH, PTPRA, ATR, GSTZ1) in three sibling patients suffering from lung cancer." (PMID 35712480, 2022). "Moreover, the findings revealed that circRNA_PTPRA overexpression significantly inhibited lung cancer cell proliferation and induced cell apoptosis, and all these changes were attenuated through up-regulation of miR-582-3p." (PMID 35549985, 2022). "Thus, the circRNA_PTPRA/miR-582-3p axis could be a latent biomarker and target for lung cancer therapy." (PMID 35549985, 2022).
hepatocellular carcinoma (2 papers, 2021 to 2022). A malignant tumor that arises from hepatocytes. "Lastly, we noticed one shared integrated gene in the current CT3 CAR T cells targeting GPC2, PTPRA, which was also found in the CAR (hYP7) T cells targeting GPC3 in hepatocellular carcinoma from our previous study, although at different integration sites." (PMID 34195677, 2021). "It has been reported that miR-582-3p can affect the progression of hepatocellular carcinoma cells by targeting circRNA HIPK3 and circRNA PTPRA, but the regulation of targeted mRNA has not been reported Therefore, miR-582-3p was selected for further study in this project." (PMID 35386287, 2022).
neuroblastoma (2 papers, 2014 to 2021). Neuroblastoma (NB) is the most common solid, extracranial childhood tumor. "Although PTPRA gene mutations in neuroblastoma are uncommon, a missense variant in the PTPRA PTP D1 domain has been associated with low survival of patients." (PMID 34957126, 2021). "PTPRA (RPTPα) has been documented to be involved in neuronal differentiation, as well as in neuroblastoma cell motility, in association with dephosphorylation and activation of Src, a PTPRA substrate shared by other cell types." (PMID 34957126, 2021). "PTPRA is highly expressed in SH-SY5Y neuroblastoma cells, whereas the related PTPRE (RPTPε) is expressed at low levels but induced upon retinoic acid differentiation." (PMID 34957126, 2021). "The possibility exists that the use of PTPRA/PTPRE inhibitors could complement the use of Src inhibitors in neuroblastoma therapies." (PMID 34957126, 2021).
bladder cancer (1 paper, 2023). "Abnormally expressed circ-PTPRA eliminated the enhancement of the malignant cell phenotype mediated by IGF2BP1 in bladder cancer." (PMID 37304234, 2023).
colon cancer (1 paper, 2021). "PTPRA regulates cellular contractility through SFKs and myosin light-chain kinase (MLCK) and its presence is required for colon cancer cell invasiveness." (PMID 33710332, 2021).
colorectal cancer (1 paper, 2008). A primary or metastatic malignant neoplasm that affects the colon or rectum. "Our results provide evidence for frameshift mutations in six of these PTP genes (PTPN21, PTPRS, PTPN5, PTPN23, PTPRA, PTPRE) affecting about 32% of MSI-H colorectal cancers." (PMID 19000305, 2008).
epidermoid carcinoma (1 paper, 2022). "High expression of PTPRA led to the dephosphorylation of SRC and thereby FAK mediated cell migration in epidermoid carcinoma cells." (PMID 36393868, 2022).
head and neck cancer (1 paper, 2022). A primary or metastatic malignant neoplasm affecting the head and neck. "PTPRA, an upstream phosphatase of SRC is reported for its oncogenic role and is highly expressed in head and neck cancers." (PMID 36393868, 2022).
Intellectual disability (1 paper, 2014). "The patient carrying the PTPRA 174620_174623dupTGAT mutation was a male diagnosed with SCZ and comorbid intellectual disability at the age of 27, while he was enrolled in our study." (PMID 25393624, 2014).
liver fibrosis (1 paper, 2021). "Moreover, miR-146a-5p is known to attenuate liver fibrosis through the regulation of fibrosis-associated pathways, such as TGF-β/SMAD, Wnt/β-catenin, LPS/TLR4/NF-κB, and PTPRA-SRC." (PMID 34796180, 2021).
Parkinson disease (1 paper, 2022). A progressive degenerative disorder of the central nervous system characterized by loss of dopamine producing neurons in the substantia nigra and the presence of Lewy bodies in the substantia nigra and locus coeruleus. "In this study we identified a rare, functional PTPRA variant that segregates with parkinsonism in a multiplex family." (PMID 35900966, 2022). "Does a rare mutation in PTPRA contribute to the development of Parkinson’s disease?" (PMID 35900966, 2022). "While parkinsonism status of participants of gnomAD is not disclosed, it would be mistaken to assume that all PTPRA p.R223W carriers develop PD." (PMID 35900966, 2022).
squamous cell lung carcinoma (1 paper, 2020). A carcinoma arising from squamous bronchial epithelial cells. "PTPRA was reported to promote the cell cycle progression and lead to poor prognosis in squamous cell lung cancer." (PMID 32545802, 2020).
tumor (6 papers, 2008 to 2024). "Possibly, MYC increases the levels of PTPRA, activating the function of this gene as a tumor suppressor, enabling cell signaling events, coordinating the control of proliferation, apoptosis, survival, migration and invasion." (PMID 33351778, 2020). "CDKN3 and PTPRA were expressed in tumor tissue samples from patients of both genders." (PMID 33351778, 2020). "Circ-PTPRA suppresses EMT in NSCLC cell lines through the circ-PTPRA/miR-96-5p/RASSF8/E-cadherin axis and is downregulated in NSCLC tumor." (PMID 36338714, 2022). "PTPRA and CDKN3 proved to be important for assessing tumor progression in the early and advanced stages." (PMID 33351778, 2020). "We also emphasize the importance of PTPRA and CDKN3, which are promising to assess tumor progression in early and advanced stages of the GC, without differentiating the histological types." (PMID 33351778, 2020).
cancer (5 papers, 2014 to 2024). A tumor composed of atypical neoplastic, often pleomorphic cells that invade other tissues. "In gastric tissue, the expression of PTPN4, PTPRA, and PTPRS were increased in cancer tissue compared with normal tissue." (PMID 30126387, 2018).
psychiatric disorder (1 paper, 2014). A disorder characterized by behavioral and/or psychological abnormalities, often accompanied by physical symptoms. "Also, our results may help provide genetic clues for the involvement of the PTPRA gene in the pathogenesis of psychiatric disorders." (PMID 25393624, 2014).
PTPRA also shares sentences with these, for which no sentence is quoted: infection (2 papers); pancreatic cancer (2); autism spectrum disorder (1); breast tumor (1); Huntington disease (1); invasive breast carcinoma (1); lung adenocarcinoma (1); memory impairment (1); neurodevelopmental disorder (1); ovarian carcinoma (1); Parkinsonism (1); rectum adenocarcinoma (1); type 1 diabetes (1).